EPHA10 (EPH receptor A10)
Diseases named in the same sentence as EPHA10 in open-access papers (continued):
Sharing a sentence is not in itself a finding about the gene and the disease.
tumor (18 papers, 2013 to 2025). "The anti-tumor effect of anti-EphA10 IgG in vivo was caused primarily by CDC effects." (PMID 26678395, 2015). "In contrast, EphA6 and EphA10 displayed elevated expression in the C3 and C5 subtypes, suggesting a potential tumor-suppressive effect." (PMID 38952552, 2024). "EphA10-specific CAR T-cells have been shown to inhibit in vivo tumor growth in an orthotopic MDA-MB-231 tumor model." (PMID 38201551, 2023). "Among other anti-EphA10 monoclonal antibodies, clone #4 caused tumour regression and boosted the activation of CD8+ tumour-infiltrating cytotoxic T lymphocytes (CTLs) in vivo, while clone #9 triggered EphA10 internalisation in TNBC." (PMID 36830852, 2023). "A previous study reported that EphA10 drives tumor progression and immune evasion by regulating the MAPK/ERK cascade in LUAD, and the MEK inhibitor U0126 significantly reversed the promoting effect of EphA10 overexpression on LUAD cells." (PMID 36159575, 2022). "The targeting of EPHA2, EPHA10, EPHB4, ephrin-A2, ephrin-A4, as well as ephrin-B2 in BC cells or xenograft models is associated with apoptosis induction, tumor regression, anticancer immune response activation, and impaired cell motility." (PMID 36499598, 2022). "In vivo, the anti-EPHA10 monoclonal antibody clone #4 induced tumor regression, as well as promoted the activation of CD8+ tumor-infiltrating cytotoxic T lymphocytes (CTLs)." (PMID 36499598, 2022). "To evaluate the effects of EPHA10 on OSCC tumor growth and lymphatic metastasis, we ablated EPHA10 expression in LN1-1 cells using lentiviral shRNA." (PMID 33436772, 2021). "The average tumor weight was 0.2278 ± 0.03017 g (n = 9) and 0.0475 ± 0.01191 g (n = 8) in mice receiving control cells and EPHA10 knockdown LN1-1 cells, respectively." (PMID 33436772, 2021). "EphA10 is down-regulated in triple-negative BCs, and an anti-EphA10 monoclonal antibody can suppress tumor growth." (PMID 34221956, 2021). "Analysis of tumor volumes showed that anti-EphA10 neutralizing monoclonal antibody inhibited tumor growth in a concentration-dependent manner." (PMID 33504115, 2021). "Targeting EPHA10 by anti-EPHA10 monoclonal antibodies significantly suppressed tumor growth in xenograft mouse models of triple-negative breast cancers." (PMID 33436772, 2021). "EPHA10 knockdown suppressed in vivo tumor growth and in vitro sphere formation, but did not affect cell proliferation." (PMID 33436772, 2021). "EphA10 is redistributed in cytoplasm where it promotes tumor invasion and metastasis (invasive cell)." (PMID 28427223, 2017). "Tumor mass with similar size was collected for weighting, and re-identifying in expression pattern of EPHA10 isoforms." (PMID 28427223, 2017). "Tracing EPHA10 isoforms result in a potentially satisfied prediction of tumor development and progression." (PMID 28427223, 2017). "Differently, EphA10 is generally up-regulated and significantly increased in tumor-size enlargement (P=0.042) and TNM stage severity (P=0.002)." (PMID 28427223, 2017). "In para-aortic lymph nodes, tumor metastases show to be shrunken to 0.63 fold in number and 0.58 fold in average weight than the ones with EphA10s−/EphA10+ metastases." (PMID 28427223, 2017). "A reduction of EphA10 in vivo significantly weakened tumor dynamic, and leads to a promising outcome." (PMID 28427223, 2017). "On the other hand, the groups treated with dimeric BsAb (EphA10/CD3) showed tumor growth that was significantly inhibited in a dose-dependent manner." (PMID 26678395, 2015). "In this study, we report the creation and initial testing of a novel BiTE class BsAb, (EphA10/CD3), which stimulates T cells to kill tumor cells that express EphA10 antigens." (PMID 26678395, 2015). "Similar to BsAb of the BiTE class, BsAb (EphA10/CD3) induced efficient tumor cell lysis at much lower concentrations than those required for standard mAb therapies." (PMID 26678395, 2015).
tumor (continued). "Redirected T-cell lysis was observed when monomeric and dimeric BsAb were added to EphA10-overexpressing tumor cells in vitro." (PMID 26678395, 2015). "Dimeric BsAb (EphA10/CD3) also showed significant anti-tumor effects in human xenograft mouse models." (PMID 26678395, 2015). "Here, we first analyzed the statistical relationship between EphA10 mRNA expression in clinical tumor tissues and their clinicopathological parameters." (PMID 24403271, 2013). "Although the effects of these CAR T-cells remain to be tested in immunocompetent models, anti-EphA10 antibodies increased the infiltration and activity of cytotoxic T-cells in a syngeneic 4T1 tumor model, suggesting that blocking EphA10 on TAMs/MDSCs restores T-cell activity." (PMID 38201551, 2023). "Furthermore, targeting of EPHA10, EPHB4, ephrin-A2, and ephrin-A4, as well as ephrin-B2 in BC cells or xenograft models was associated with tumor regression, anticancer T-cell activation, and impaired cell motility." (PMID 36499598, 2022). "Collectively, EPHA10 supports tumor growth and lymph node metastasis of OSCC cells in vivo." (PMID 33436772, 2021). "We demonstrated that EPHA10 supports in vivo tumor growth and lymphatic metastasis of OSCC cells." (PMID 33436772, 2021). "Previous study showed that inhibiting intercellular communication by targeting EPHA10 could boost anti-tumor immunity by reducing PD-L1 expression." (PMID 33526018, 2021). "The results of an in vitro cytotoxicity assay also demonstrated that a dimeric BsAb (EphA10/CD3) could induce redirected tumor killing by CTL at a low concentration (10−1 μg/mL)." (PMID 26678395, 2015). "Similarly, EPHA10 knockdown led to significantly lower tumor volume compared to controls." (PMID 33436772, 2021). "Furthermore, the in vivo efficacy of dimeric BsAb (EphA10/CD3) in a xenograft model showed that it could inhibit tumor growth at low doses (1, 10 μg), similar to the effective concentration ranges for other BsAbs." (PMID 26678395, 2015). "Consequently, the relationship between EphA10 and clinical tumor progression is poorly understood." (PMID 24403271, 2013). "As another example, a neutralizing mAb against EphA10 showed anti-tumor activity in a mouse model of TNBC, where EphA10 overexpression is known to act as a malignant factor." (PMID 36293051, 2022). "Signaling by EPHA10 and its ligand, EFNA4, promotes OSCC cell migration and tumor spheroid formation through induction of NANOG mRNA expression via ERK activation." (PMID 33436772, 2021). "We also note > two-fold increased expression in some members of the Ephrin pathway (EPHA10, EPHB1, EPHB2, EPHB3) that may play key roles in tumor progression, invasion, and immune evasion." (PMID 38704802, 2024). "Only EphA10 was necessary for PD-L1 overexpression and the removal of EphA10 from mouse 4T1 cancer cells greatly enhanced CD8+ T-cells, T-cell activity, and tumour cell death, and decreased tumour growth." (PMID 36830852, 2023). "In this study, we report creation of a novel bispecific antibody (BsAb) binding both EphA10 and CD3, thereby forming a bridge between antigens expressed on both tumor and immune cells and promoting recognition of tumor cells by immune cells and redirection of cytotoxic T cells (CTL)." (PMID 26678395, 2015). "Thus, we are now constructing various BsAbs (EphA10/CD3) from other BsAb formats (include tandem scFv and single-chain Diabody) and different anti-CD3 Ab in order to improve its anti-tumor effect." (PMID 26678395, 2015). "Furthermore, dimeric BsAb (EphA10/CD3) was more cytotoxic than monomeric BsAb, with efficient tumor cell lysis elicited by lower concentrations (≤10−1 μg/mL) and a lower effector to target (E/T) cell ratio (E/T = 2.5)." (PMID 26678395, 2015). "Also, tumor/nontumor (T/N) ratios of EFNA4, NANOG, OCT4, and EPHA10 mRNA expression had averages of 1.39, 1.25, 2.37, and 1.03, respectively." (PMID 33436772, 2021).
cancer (12 papers, 2015 to 2025). A tumor composed of atypical neoplastic, often pleomorphic cells that invade other tissues. "An illustration of this was found in the close association between EphA3 expression and elevated stromal score across diverse cancers, whereas EphA10 expression demonstrated an inverse pattern." (PMID 38952552, 2024). "In OSCC cells, EPHA10 plays a critical role in linking external stimuli (EFNA4 or other ligands) to the internal signal transduction that leads to cancer cell migration and spheroid formation." (PMID 33436772, 2021). "Examples include Eph‐dependent signalling in endocrine and immune systems as well as in cancer cell proliferation, where links between EphB6 and EphA10 and canonical kinases such as EphB4, EphB1 and Src‐family kinases have been established." (PMID 32053275, 2020). "We also confirmed the target-specific cytotoxicity of BsAb (EphA10/CD3) by testing other EphA10-positive cancer cell lines." (PMID 26678395, 2015). "Therefore, some catalytically defective RPTKs involved in tumorigenesis, such as PTK7, Erb-B2 receptor tyrosine kinase 3 (ErbB3), and EPH receptor A10 (EphA10), are considered target molecules for cancer therapy." (PMID 36293051, 2022). "Based on the publicly available clinical datasets, we found that EPHA10 mRNA expression varied among different cancer types, indicating that the effect of EPHA10 was tissue-specific and likely dependent on the milieu of binding partners and related target gene regulation in a given cell type." (PMID 33436772, 2021). "Although the dimeric form of the BsAb against EphA10/CD3 shows promise as a new therapeutic molecule for the treatment of EphA10-positive cancer, there are still potential problems that could affect its translation to the clinic." (PMID 26678395, 2015). "Moreover, cytoplasmic EphA10 played a strong role in promoting invasion and metastasis of cancer." (PMID 28427223, 2017). "Concerning the poorly characterized Class 2 pseudokinase receptors EPHA10 and EPHB6 whose expression is often disregulated in cancer, their ability to bind kinase inhibitors offer opportunities for future therapeutics." (PMID 38773263, 2024). "However, the roles of EPHA10 in development of cancer stemness remain unknown." (PMID 33436772, 2021). "In vivo studies have indicated the dimeric BsAb (EphA10/CD3) is effective against EphA10-positive cancer tumors, however, we did not demonstrate a significant difference compared with anti-EphA10 IgG." (PMID 26678395, 2015). "However, EPHA10 expression was not significantly different when comparing data from cancer and normal tissue in available HNSCC datasets." (PMID 33436772, 2021).
infection (1 paper, 2017). The state of being infected such as from the introduction of a foreign agent such as serum, vaccine, antigenic substance or organism. "We modified expression patterns of EphA10s and EphA10 in MDA-MB-231 cells by lentiviral infection for a further investigation." (PMID 28427223, 2017). "In Western Bolt, knocking down EphA10 by lentiviral infection in MCF-10A cells leads to a slightly increase of pECAD, while in MDA-MB-231 cells results in a shrink of pECAD with a decrease of N-Cadherin (NCAD)." (PMID 28427223, 2017).
EPHA10 also shares sentences with these, for which no sentence is quoted: hepatocellular carcinoma (2 papers); adenocarcinoma (1); esophageal carcinoma (1); glioma (1); liver cancer (1).